RN7SL148P (RNA, 7SL, cytoplasmic 148, pseudogene)
Gene: Miscellaneous RNA gene on chromosome 1 (244,103,932 to 244,104,210, forward strand). Ensembl gene ENSG00000244066.
Homologues: Orthologues: chimpanzee Metazoa_SRP (98% identical), macaque Metazoa_SRP (81% identical). Paralogues in human: RN7SL1 (84% identical), RN7SL3 (84% identical), RN7SL2 (83% identical), RN7SL126P (82% identical), RN7SL786P (81% identical), RN7SL416P (81% identical), RN7SL709P (81% identical), RN7SL448P (80% identical), RN7SL664P (80% identical), RN7SL566P (80% identical), RN7SL630P (80% identical), RN7SL147P (80% identical), and 703 more.